EPO (erythropoietin)
Description:
Hormone involved in the regulation of erythrocyte proliferation and differentiation and the maintenance of a physiological level of circulating erythrocyte mass. Binds to EPOR leading to EPOR dimerization and JAK2 activation thereby activating specific downstream effectors, including STAT1 and STAT3.
Synonyms: EP; DBAL; ECYT5; MVCD2
Tractability: Antibody: UniProt places it where antibodies can reach, with high confidence; its Gene Ontology location is reachable by antibodies, with high confidence; UniProt predicts a signal peptide or a membrane-spanning region.
Target class: Secreted protein
Gene: Protein-coding gene on chromosome 7 (100,720,468 to 100,723,700, forward strand). Ensembl gene ENSG00000130427.
Subcellular location: Secreted
Pathways (Reactome):
Signal Transduction: Erythropoietin activates Phosphoinositide-3-kinase (PI3K); Erythropoietin activates Phospholipase C gamma (PLCG); Erythropoietin activates RAS; Erythropoietin activates STAT5; Signaling by Erythropoietin
Cellular responses to stimuli: Regulation of gene expression by Hypoxia-inducible Factor
Gene Ontology:
Molecular function: cytokine activity; erythropoietin receptor binding; hormone activity; protein binding; protein kinase activator activity
Biological process: cell surface receptor signaling pathway via STAT; cellular hyperosmotic response; erythrocyte differentiation; erythropoietin-mediated signaling pathway; negative regulation of calcium ion transport into cytosol; negative regulation of erythrocyte apoptotic process; negative regulation of intrinsic apoptotic signaling pathway in response to osmotic stress; negative regulation of transcription by RNA polymerase II; positive regulation of cell population proliferation; positive regulation of DNA-templated transcription; positive regulation of Ras protein signal transduction; blood circulation; signal transduction; acute-phase response; negative regulation of apoptotic process; positive regulation of activated T cell proliferation; positive regulation of ERK1 and ERK2 cascade; positive regulation of neuron differentiation; positive regulation of neuron projection development; response to axon injury; response to dexamethasone; response to electrical stimulus; response to estrogen; response to hyperoxia; response to hypoxia; and 7 more
Cellular component: cell surface; extracellular region; receptor complex; cell body
Genetic constraint (gnomAD): Loss-of-function variants: 12 observed, 23.73 expected, observed/expected ratio (o/e) 0.51, 90% interval 0.32 to 0.82. The upper end of that interval is the gene's LOEUF score, 0.82, which puts it in group 3 of 6, group 1 being the genes least tolerant of losing a copy. Missense variants: 210 observed, 246.62 expected, observed/expected ratio (o/e) 0.85, 90% interval 0.76 to 0.95. Synonymous variants: 107 observed, 108.17 expected, observed/expected ratio (o/e) 0.99, 90% interval 0.85 to 1.16.
Homologues: Orthologues: chimpanzee EPO (99% identical), macaque EPO (92% identical), pig EPO (82% identical), dog EPO (81% identical), rat Epo (81% identical), mouse Epo (79% identical), rabbit EPO (78% identical), guinea pig EPO (75% identical), tropical clawed frog epo (34% identical), zebrafish epoa (33% identical), zebrafish epob (32% identical).
Diseases named in the same sentence as EPO in open-access papers:
EPO is named in the same sentence as 723 diseases in open-access papers, as found by Europe PMC text mining. Sharing a sentence is not in itself a finding about the gene and the disease. The quoted sentences say what the papers report.
anemia (2,311 papers, 1982 to 2026). A reduction in the number of red blood cells, the amount of hemoglobin, and/or the volume of packed red blood cells. "The new guideline emphasises the need for a comprehensive evaluation of the patient at the time of diagnosis, to identify additional causes of anaemia other than erythropoietin insufficiency." (PMID 41604211, 2026). "Negative regulators: chronic inflammation—cytokines such as IL-1β and TNF-α suppress EPO transcription; and CKD—loss of EPO-producing cells leads to anemia." (PMID 41012526, 2025). "Erythropoietin (Epo) can be an effective anemia treatment, but is ineffective or contraindicated in anemia associated with cancer or chronic disease." (PMID 41379768, 2025). "While this finding reflects acute blood loss and iron deficiency as major factors of ICU-acquired anemia, the effectiveness and safety of erythropoietin were unexplored." (PMID 40152861, 2025). "Although urinary EPO losses do not necessarily appear to be accompanied by a decrease in adequate plasma concentrations of EPO, urinary losses have been shown to contribute to EPO deficiency anemia." (PMID 40620843, 2025). "A recent RCT showed that in HD patients with anemia and vitamin D deficiency, vitamin D therapy (50,000 IU/month) for 6 months was associated with improved Hb levels and decreased dosages of erythropoietin agents." (PMID 41373702, 2025). "Experiments performed in mice revealed that phlebotomy and anemia were associated with increased expression of EPO mRNA." (PMID 40027896, 2025). "A substantial body of clinical and experimental research indicates that patients with heart failure (HF) are particularly susceptible to mixed-type anemia, primarily driven by iron deficiency and inadequate erythropoietin production." (PMID 41367439, 2025). "Multiple factors contribute to post-transplant anemia, including iron deficiency, erythropoietin insufficiency, immunosuppressive medication effects, graft dysfunction or rejection, infections, malignancy, acute and chronic bleeding." (PMID 41458512, 2025). "Recombinant human erythropoietin is commonly used in clinical settings to treat anemia associated with cancer and chemotherapy." (PMID 40457205, 2025). "These pathophysiologic mechanisms—especially reduced erythropoietin synthesis and iron deficiency represent the two principal contributors to anemia in CKD, and form the clinical foundation for our study's diagnostic focus." (PMID 41282024, 2025). "The global use of erythropoietin for MF-associated anemia is frequent, particularly in patients with low serum erythropoietin levels." (PMID 40094998, 2025). "Our study confirms that IV iron therapy is significantly effective than oral iron in improving iron deficiency anemia in diabetic patients with CKD receiving erythropoietin." (PMID 40980376, 2025). "Telomere shortening demonstrates a possible association with anemia and erythropoietin resistance in patients with CKD undergoing hemodialysis." (PMID 40244253, 2025). "This study addresses the critical challenge of managing iron deficiency anemia in diabetic patients with CKD who are receiving recombinant EPO therapy." (PMID 40980376, 2025). "Collectively, the results allow the proposition that rs1149222 fosters an IL-1β-dominated milieu that, through hepcidin induction and erythropoietin suppression, yields the mild inflammation-associated anemia noted in heterozygotes." (PMID 40869618, 2025). "It should be noted that systemic inflammation interacts intricately with renal function, contributing to impaired iron metabolism and attenuated erythropoietin production/responsiveness, ultimately leading to anemia and iron deficiency." (PMID 41143188, 2025). "Previous evidence has shown that EPO use in cancer-associated anemia can increase the risk of venous thromboembolism and mortality." (PMID 41010667, 2025). "This anemia has several causes, including inflammation, reduced EPO production, and poor hepcidin clearance by the damaged kidneys." (PMID 41007630, 2025).
anemia (continued). "Anemia occurs in CKD mainly because of defective erythropoietin production but can result from other causes such as inflammation or uremia." (PMID 41357357, 2025). "Most physicians treat MF-associated anemia with erythropoietin, followed by prednisone and immunomodulatory drugs (IMIDs, i.e., thalidomide or lenalidomide)." (PMID 40094998, 2025). "Ultimately, impaired erythropoiesis, reduced erythropoietin production, shortened red blood cell survival, and iron dysregulation collectively cause anemia." (PMID 41179861, 2025). "In chronic kidney disease (CKD), anaemia results from factors like shortened red cell lifespan, functional iron deficiency, diminished erythropoietin (EPO) production, and EPO resistance." (PMID 41142174, 2025). "Preterm infants have an immature hematopoietic system, reduced erythropoietin production, a predisposition to anemia due to low iron stores and frequent transfusion requirements." (PMID 40217979, 2025). "This pattern highlights the numerous factors impacting kidney function, erythropoietin synthesis, and bone marrow activity in the context of anemia associated with CKD." (PMID 40497218, 2025). "Among those receiving hemodialysis, anemia most often develops because of reduced erythropoietin (EPO) production, disruptions in iron metabolism associated with chronic inflammation, blood loss, and oxidative stress." (PMID 41459576, 2025). "CKD patients on dialysis increased their susceptibility to anemia after B19V infection due to the occurrence of deficient erythropoietin production, weakened immune response, and decreased erythrocyte survival, which can lead to serious anemia." (PMID 40143234, 2025). "Anemia, largely caused by insufficient erythropoietin production and iron imbalance, increases cardiac workload and fosters left ventricular hypertrophy." (PMID 41470171, 2025). "This decrease in erythropoietin levels can further increase the risk of anemia in older individuals with diabetes." (PMID 40791804, 2025). "Iron deficiency is one of the causes of anemia in CKD alongside decreased production of erythropoietin (EPO)." (PMID 41034675, 2025). "Renal injury also reduces the clearance of coagulation factors and fibrin degradation products and decreases erythropoietin levels, causing anemia and increased blood viscosity, which exacerbate coagulopathy." (PMID 40098952, 2025). "As a result, HIF-2α inhibition suppresses EPO synthesis, causing anemia, a well-documented on-target adverse effect (AE) of belzutifan." (PMID 40920370, 2025). "The primary cause of this anemia is the insufficient production of endogenous erythropoietin, which can result from either functional or absolute deficiencies of iron." (PMID 40655101, 2025). "It is worth mentioning that similar erythropoietin (40%) and steroid (20.5%) utilization rates for MF-associated anemia were also noted in Italy." (PMID 40094998, 2025). "The main causes of anemia among CKD patients are a deficiency of erythropoietin (EPO), a hormone required for red blood cell (RBC) production, chronic inflammation, poor gastrointestinal iron absorption, and blood loss." (PMID 40508930, 2025). "Some examples of these therapeutic applications are: Recombinant human erythropoietin (EPO) is used to treat anemia associated with chronic kidney disease and has improved the quality of life for kidney dialysis patients." (PMID 40362303, 2025). "During pregnancy, EPO is utilized to manage iron-deficiency anemia, often in conjunction with iron supplementation to optimize hematologic outcomes." (PMID 41012526, 2025). "Recombinant human EPO and its variants have been used as erythropoiesis‐stimulating agents (ESAs) for the treatment of anemia for several decades." (PMID 40960423, 2025).
anemia (continued). "Althought sunitinib-induced anemia was associated with an adaptative response to systemic hypoxia, we demonstrated that erythropoietin (EPO) concentrations in the total bone marrow of sunitinib-treated mice were significantly lower than in untreated mice." (PMID 40253376, 2025). "A first-line treatment to manage splenomegaly in MF is ruxolitinib (93.5%), whereas MF-associated anemia is usually treated with erythropoietin (51.6%), followed by prednisone (22.6%), thalidomide/lenalidomide (19.4%), and danazol (6.5%)." (PMID 40094998, 2025). "Inflammation, hemodilution, iron deficiency, erythropoietin levels, prescription medicine, and medullary dysfunction have all been linked to anemia either alone or in combination." (PMID 41254796, 2025). "CKD can also cause a series of serious complications, among which its associated anemia is caused by decreased erythropoietin (EPO) production due to decreased kidney function." (PMID 40866816, 2025). "Erythroferrone is responsible for hepcidin suppression during periods of increased erythropoietic activity governed by the erythropoietin hormone and allows for compensatory iron absorption during the recovery from blood loss-induced anemia." (PMID 40661067, 2025). "For example, anaemia is a commonly identified risk factor and included as a treatment target in guidelines (e.g. using erythropoietin)." (PMID 40599823, 2025). "EPO is used to treat anemia associated with chronic kidney disease clinically and plays a role in maintaining metabolic homeostasis and regulating fat mass." (PMID 39996752, 2025). "These cytokines are linked to inadequate endogenous erythropoietin production in response to anemia, suppressed erythropoietic response of red cell precursors, and hindered intestinal iron absorption." (PMID 40364122, 2025). "Patients experiencing anemia with preserved kidney function exhibit EPO levels that are 10 to 100 times greater than those observed in patients with CKD-associated anemia." (PMID 40364122, 2025). "The purification of EPO, the cloning of its gene, and subsequent development of recombinant EPO (rEPO) revolutionized the treatment of anemia associated with EPO deficiency." (PMID 40960423, 2025). "Clinical trials and observational studies indicate that EPO biosimilars can achieve comparable hemoglobin (Hb) targets to the reference EPO products in patients with anemia linked to CKD or induced chemotherapy." (PMID 41012526, 2025). "On the other hand, addressing postpartum anemia with erythropoietin has been associated with improved breastfeeding outcomes." (PMID 40129756, 2025). "In regenerative anemia, elevated EPO levels respond to decreased HGB levels, reflecting a loss of erythrocytes due to hemolysis or bleeding." (PMID 40574855, 2025). "In CKD patients, even though anemia develops primarily as a result of the decreased lifespan of RBCs caused by the low production of erythropoietin and iron deficiency, eryptosis seems to be a fundamental contributing factor." (PMID 40592821, 2025). "ERFE is especially critical early in the response to increased RBC demands as shown in ERFE-deficient mice, in which hepcidin suppression after blood loss or EPO treatment is delayed, thus slowing anemia recovery by several days compared to wild type animals." (PMID 41007630, 2025). "Patients with ESRD experience a deficiency of erythropoietin production and decreased red blood cell production, resulting in anemia and physical symptoms due to uremia gradually." (PMID 40281447, 2025). "Our study shows that renal insufficiency is prevalent among PLWH, can impair erythropoietin production subsequently hindering erythropoiesis and causing anaemia." (PMID 39901231, 2025). "While RBC transfusion remains the mainstay of treatment for HS-associated anemia, the patient in case I received EPO treatment prior to discharge." (PMID 41007072, 2025).
anemia (continued). "This suggests that a decreased concentration of EPO is unlikely to play a major role in SMA, which is also supported by the notion that, in malaria, circulating EPO is higher when compared to other pathologies causing the same degree of anemia." (PMID 38892340, 2024). "Anemia in KFRT patients is multifactorial but primarily caused byinsufficient erythropoietin (EPO) production." (PMID 38284551, 2024). "Despite this, many ESRD patients have erythropoietin-resistant anemia and/or anemia of inflammation and cannot tolerate additional blood loss during hemodialysis, which would further worsen their anemia, prognosis, and quality of life." (PMID 39060370, 2024). "A high percentage of approximately half of ESRD patients in the United States have been reported to suffer from anemia due to erythropoietin deficiency, resulting from impairment of erythropoietin synthesis by accumulated uremic toxins." (PMID 38251024, 2024). "Under physiological conditions, during stress erythropoiesis, anemia causes increased erythropoietin (EPO) secretion by the kidneys." (PMID 39337010, 2024). "Used routinely to manage anemia resulting from the underlying malignancy or anticancer therapy, erythropoietin (EPO) manifests prohypertensive effects." (PMID 38542413, 2024). "Anemia is the main cause of EPC expansion by increasing EPO concentration in response to oxygen deficit." (PMID 39474425, 2024). "In CKD, anemia primarily result from a relative deficiency of EPO, with additional factors such as uremic toxins, chronic inflammation, impaired iron metabolism, and shortened erythrocyte lifespan contributing to its complexity." (PMID 38311719, 2024). "In CKD dogs, anemia is mainly caused by the reduction of the production of erythropoietin (EPO), together with other mechanisms, such as chronic inflammation, disorders of iron metabolism, blood loss, and reduction in erythrocyte survival." (PMID 38787184, 2024). "Considering that the severity of albuminuria is positively associated with interstitial fibrosis, the progression of albuminuria is presumably related to decreased erythropoietin production, causing anemia." (PMID 37955878, 2024). "Mechanistically, HIF‐PH inhibitors restore HIF activity thereby inducing transcription of genes encoding EPO and EPO receptor, improving anemia." (PMID 39691241, 2024). "Pathogenesis of haemolysis and anaemia is induced by reticulocytosis reduction, the resistance to erythropoiesis, and the inhibition of erythroid precursor proliferation cause by erythropoietin." (PMID 38566916, 2024). "In patients with systemic inflammation, serum erythropoietin levels are lower compared to the individuals with a similar degree of iron-deficiency anemia." (PMID 38610814, 2024). "Yet, the most crucial cause of CKD-induced anemia is decreased serum erythropoietin (EPO), a hormone that was secreted normally by renal interstitial fibroblast." (PMID 38828426, 2024). "Apart from insufficient erythropoietin formation, iron deficiency (ID) contributes to anemia development." (PMID 38930016, 2024). "In chronic kidney disease and other conditions with impaired renal function, the production of erythropoietin, which stimulates the production of blood cells, is reduced, causing anemia." (PMID 38985383, 2024). "In CKD, impaired renal function leads to an increased loss of iron and decreased EPO production; this subsequently leads to decreased levels of systemic iron and EPO, which ultimately results in iron deficiency and anemia." (PMID 39748872, 2024). "Anemia in heart failure is multifactorial, with causes including functional iron deficiency, inflammation, gastrointestinal congestion, reduced erythropoietin production, and fluid retention." (PMID 39768541, 2024). "Thirdly, Chronic kidney disease (CKD) is recognized as a risk factor for anemia, typically usually related to erythropoietin(EPO) deficiency." (PMID 39146304, 2024).